DPY19L2P1 (DPY19L2 pseudogene 1)
Description:
Probable C-mannosyltransferase that mediates C-mannosylation of tryptophan residues on target proteins.
Gene: Transcribed unprocessed pseudogene on chromosome 7 (35,081,590 to 35,186,041, reverse strand). Ensembl gene ENSG00000189212.
Subcellular location: Membrane
Diseases named in the same sentence as DPY19L2P1 in open-access papers:
DPY19L2P1 is named in the same sentence as 4 diseases in open-access papers, as found by Europe PMC text mining. Sharing a sentence is not in itself a finding about the gene and the disease. The quoted sentences say what the papers report.
laryngeal carcinoma (2 papers, 2022 to 2024). Carcinoma that arises from the laryngeal epithelium. "For example, it has been regularly reported that laryngeal cancer tissues differentially express certain genes, including EMP1, HOXB9, DPY19L2P1, MMP1, and KLHDC7B, representing independent prognosis predictor genes of laryngeal cancer." (PMID 39452555, 2024).
glioma (1 paper, 2022). A benign or malignant brain and spinal cord tumor that arises from glial cells (astrocytes, oligodendrocytes, ependymal cells). "Considering that immune cells are an important component of the tumour environment, glioma‐derived exosomes would deliver CT62, DPY19L2P1, and KCNH1‐IT1 to immune cells, regulating the tumour immune microenvironment." (PMID 35194922, 2022). "Considering that immune cells are an important component of the tumor environment, glioma‐derived exosomes would deliver CT62, DPY19L2P1 and KCNH1‐IT1 to immune cells, regulating the tumour immune microenvironment." (PMID 35194922, 2022).
malignant glioma (1 paper, 2022). A grade III or grade IV glioma arising from the central nervous system. "Therefore, the low expression of CT62, DPY19L2P1, KCNH1‐IT1 and VPS33B in malignant glioma would promote the formation of M2 macrophages and thus promote malignant glioma tumorigenesis and progression." (PMID 35194922, 2022). "Fourteen genes within the tumour immune microenvironment pathway (AC020907.1, Y_RNA, TMEM72‐AS1, KRT16P2, DLX6‐AS1, AP002414.1, hsa‐miR‐424, TBPL1, NPAS2, CRY2, VPS33B, CT62, DPY19L2P1, and KCNH1‐IT1) were used to construct a model to evaluate the importance of these genes in malignant glioma." (PMID 35194922, 2022).
DPY19L2P1 also shares sentences with these, for which no sentence is quoted: tumour (1 paper).